CD63 (CD63 molecule)
Diseases named in the same sentence as CD63 in open-access papers (continued):
Sharing a sentence is not in itself a finding about the gene and the disease.
tumor (continued). "Analysis revealed that the tumor cells were immunopositive for vimentin, microphthalmia transcription factor, S100, CD1a, CD10, CD63, and folliculin, but immunonegative for cytokeratin, α-smooth muscle actin, HMB45, Melan-A, and PNL-2." (PMID 27871249, 2016). "For example, we identified several members of the tetraspanins family (Tetraspanin-14, CD9, CD63, and CD81 antigens) to be increased in tumor-derived exosomes from the non-invasive cell line, MCF-7." (PMID 25798887, 2015). "If the pro-tumor activity of TIMP-1 is MMP-independent and exerted through its indirect promotive effect on CAFs and the TIMP-1 receptor, CD63 expressed by CAFs." (PMID 24143225, 2013). "We have addressed the variation in expression of some common exosomal proteins (CD9, CD81, CD63, Rab5, HSP70, TSTA3) and tumour-specific proteins (i.e. TM9SF4) in plasma exosomes from patients with different solid tumours." (PMID 26082317, 2013). "Used capture and detection antibodies can recognize exosome-specific markers (Rab5, CD63 and CD9), melanocyte-specific proteins (MelanA, MCAM, Tyrosinase) and tumor markers (CEACAM, CD44)." (PMID 26082068, 2012). "Since EVs express tetraspanin family proteins such as CD63, CD81, and CD9, circulating EVs could be detected by these proteins as well as other tumor-specific markers." (PMID 40679665, 2025). "Alongside HEK293T cells, human primary tumor cell lines MDA-MB-231, MCF-7, and T47D were treated with various dosages of MCP-PhoCl-CD9 and MCP-PhoCl-CD63 VSV-G+ EVs." (PMID 41271724, 2025). "Targeting EV biogenesis or sorting mechanisms such as Rab27A inhibition or the interactions between CD63, LAMB1 and CD147 could provide novel therapeutic avenues to reverse resistance and re‐sensitize tumours to GCB." (PMID 41159684, 2025). "Our results demonstrated that laminin, not fibronectin, is the primary target of tumor-derived sEVs containing CD63, CD81, or CD9." (PMID 40304687, 2025). "It is possible that CD63/81+ and CD9/63/81+ sEVs may be tumor-derived, although further studies are needed to identify the origin of these vesicles." (PMID 38892225, 2024). "Tumor-derived exosomes (uniformly round or oval, size range of 30–120 nm, marker proteins CD81, CD63,TSG101) miR-146a-5p can activate the anti-oncogene WWC2-mediated Hippo-YAP signaling pathway and change the dynamics of F-actin/G-actin, eventually leading to CC metastasis." (PMID 39165926, 2024). "The enrichment of CD63/81+ and CD9/63/81+ sEVs in post-brachytherapy samples suggests that these subpopulations may be tumor-derived." (PMID 38892225, 2024). "Furthermore, when we used super-resolution nanoimaging, we were able to confirm that the EBC of human lung tumor-bearing mice contained human tumor-derived EVs (positive for CD9, CD63, and CD81)." (PMID 38863869, 2024). "To determine whether expression of tagged CD63 would affect tumor growth kinetics, we established a human PDAC cell line stably expressing CD63-GFP and orthotopically implanted the clone and its parental counterpart in the pancreas of immunodeficient mice." (PMID 38383468, 2024). "We experimentally confirmed the capture and release of intact CD63-GFP+ EVs produced in large amounts by our LM-3475 cells in vitro prior to purifying low abundance (i.e., compared to tissue culture) human tumor-derived EVs from the EBC of lung tumor-bearing mice." (PMID 38863869, 2024). "Genetic engineering involves the fusion of tumor-targeting or tumor-penetrating peptides with transmembrane proteins, including LAMP2B, PDGFR, PTGFRN, CD63, CD9, and CD81, on EVs and the expression of the fused protein in donor cells, which produce EVs with the functional peptides on the surface." (PMID 38796692, 2024). "Double-label IF staining of 231 LuT3 tumor tissue unveiled a significant uptick in colocalization of CD63 and LAP-TGF-β1 as opposed to 231 Parental tumor tissue." (PMID 38664722, 2024).
tumor (continued). "Finally, CD63-silenced melanoma cells showed enhanced motility, invasiveness, EMT and in vivo tumor growth." (PMID 36941633, 2023). "Recent data support the high level of versatility of the technique, with the identification of a series of housekeeping proteins, such as Rab5b, CD81, and CD63, and tumor-specific markers, such as PSA, but also surrogate tumor markers, such as Cav-1 and carbonic anhydrase." (PMID 37296842, 2023). "In addition, exosome-specific markers TSG101, CD9, CD63 and CD81 were evaluated in tumor-derived exosomes through different methodologies." (PMID 35804987, 2022). "The serum levels of CD63+-, CD41+, and CD61+ EVs reflected the tumor burden in patients with PDAC." (PMID 35350978, 2022). "The serum levels of CD63+-EVs, CD41+-EVs, CD61+-EVs, and CA19-9 decreased significantly after surgical resection, demonstrating that EVs are increased in sera of patients depending on the tumor burden." (PMID 35350978, 2022). "For instance, In tumor-immune interface-3, pro-tumor expression markers are TIMP1, a member of MMPs involved in the degradation of the extracellular matrix, whereas IGFBP4, PFDN5, CD63 repress tumor progression." (PMID 35835774, 2022). "In that report, anti-CD9 and CD63 antibodies did not affect vascular generation in the primary tumor, and, moreover, these antibodies did not affect tumor cell proliferation and invasion." (PMID 36289745, 2022). "The size distribution and surface topography of these two exosomes were not significantly different, but the expression of CD63 in early tumor exosome (E-exosome) was significantly lower than that in advanced tumor exosome (A-exosome)." (PMID 34093824, 2021). "We were unable to observe any CD63 specific signal in the plasma-derived EVs as opposed to the CD63 in EVs derived from various human tumour cell lines including PC9." (PMID 34725463, 2021). "Because HER2, IGF1R, MET and NTRK2 are also present in tumor-derived exosomes that play important roles in tumor progression, we aimed to investigate whether RAB31 control these RTKs entry into CD63-positive MVEs." (PMID 32958903, 2021). "Considering that both IL‐6 and IL‐27 contribute to tumour progression through JAK/STAT3 signalling pathway, we next elucidated whether CD63 regulated the activation of signal transducer and activator of transcription‐3 (STAT3) by Western blot analysis." (PMID 33277798, 2021). "In most instances, the protein content of CAF-EVs is comparable between different tumor types and includes proteins normally enriched in exosomes such as CD9, CD63 and CD81 and proteins involved in exosome biogenesis like ESCRT-associated proteins, Alix, TSG101, HSC70 and HSP90β." (PMID 33899109, 2021). "The reduction in size in both primary tumours and metastases suggest an impairment of tumour cell growth, which was confirmed by Ki67 staining in histological sections from tumours treated with CD9 peptide and in a lesser extent with CD63 peptide." (PMID 34012515, 2021). "However, in non-tumor cells such as dendritic cells, ALIX silencing increased MHC-II exosomal secretion but reduced CD63 presence in exosomes." (PMID 33892745, 2021). "We demonstrated that in CD63-Antares2 xenograft model mice, dasatinib at 2.5 mg/kg inhibited exosome secretion without suppressing tumor growth." (PMID 33024173, 2020). "In this context, Yuh-Ying Yeh and co-workers have identified the tetraspanin, CD9, CD63, and CD37 as abundantly expressed markers in tumor exosomes of CLL patients by flow analysis and immunoblotting, in contrast to the modest expression of CD41, CD56, and CD3." (PMID 32759810, 2020). "The effective isolation of EVs was confirmed by western blot analysis, with positive signal for the tetraspanins CD9, CD63, CD81 and Tumour Susceptibility Gene 101 (TSG101), while negative for the cellular marker calnexin." (PMID 33216826, 2020). "Immunohistochemically, the tumor cells are positive for NKI-C3 (CD63) and CD68, but negative for melanocytic and epithelial markers." (PMID 32316685, 2020).
tumor (continued). "To trace the exosome communication between GC cells under more realistic conditions, we established a co-cultivation system and transfected an RFP-tagged CD63 plasmid into MKN-45 and BGC-823 cells (exo-RFP-MKN-45 and exo-RFP-BGC-823) to label the exosomes within tumour cells." (PMID 30717751, 2019). "Nevertheless, these tumours showed induction of CK8, CK18, GRP78, CD55, CD59 and CD63 mRNAs." (PMID 30820548, 2019). "We show that IL-33 recruits eosinophils indirectly, via stimulation of tumor cell-derived chemokines, while it activates eosinophils directly, up-regulating CD69, the adhesion molecules ICAM-1 and CD11b/CD18, and the degranulation marker CD63." (PMID 31717819, 2019). "In our study, we did not score CD63 expression in immune cells, but only in tumor cells and blood vessels." (PMID 29523123, 2018). "CD63 was distributed in virtually all tumor cells and spheroids and therefore, CD63 co-expression with stem cell markers was not specifically investigated." (PMID 29523123, 2018). "By comparing the zeta potential distributions of EVs after their immunochemical reaction with normal IgG, and the anti-human CD63 and anti-human CD44 (cancer stem cell marker) antibodies, EVs of tumor origin circulating in blood were differentially detected in the real sample." (PMID 25928805, 2015). "In particular CD63 expression changed with tumour stage in a way that did not correspond to the overall number of circulating exosomes." (PMID 26082317, 2013). "Furthermore, CD63 exhibited significantly higher expression levels in the malignant cell clusters of immune cells and demonstrated a strong correlation with glycolytic genes, such as LDHA and LDHB, in tumor cells." (PMID 41573746, 2025). "The TIMP1/CD63/β1-integrin complex activates MAPK, FAK-PI3K, or YAP/TAZ signaling, which promotes cancer cell proliferation, growth, survival, migration, and EMT, regulates differentiation and inhibits apoptosis of cancer cells, ultimately leading to tumor progression and metastasis." (PMID 38360633, 2024). "Tumor location does not influence the preferential release of these sEV subpopulations; the percentages of CD63/81+ and CD9/63/81+ sEVs demonstrated a significant increase post-brachytherapy in both anterior and posterior tumors (12 anterior vs. 7 posterior pairs)." (PMID 38892225, 2024). "Interestingly, rates of communication, defined by the number of cells positive for CD63+ Exos with respect to their prevalence in the tumor, are not dependent on their frequency." (PMID 38383468, 2024). "Therefore, it is plausible to envisage that tumor cell release of CD63 and TIMP-1 via exosomes might result in the horizontal transfer of malignant traits to recipient cells, thereby promoting tumor progression and resistance to therapy." (PMID 37443843, 2023). "As a model system, we probed tumor‐cell derived EVs for CD63 expression, measuring the net fluorescence intensity, ΔICD63 = ICD63 – IIgG, wherein ICD63 and IIgG were, respectively, the signals from samples labeled with a CD63 antibody and an isotype IgG antibody." (PMID 37485618, 2023). "Interestingly, a comprehensive analysis of EV protein markers across more than 100 different human tumor and non-tumor cell lines showed that only 40% of them were positive for CD63." (PMID 35805031, 2022). "CD63 expression in tumor tissues was significantly higher than in nontumor liver tissues." (PMID 35646637, 2022). "From the experimental data, we concluded that the levels of CD63, CA125WGA, and CA15‐3WGA may be used to differentiate localized BrCa from healthy controls significantly better than the levels of conventional glycoprotein tumor markers CA125 and CA15‐3." (PMID 34423573, 2022).
tumor (continued). "Interestingly, we previously showed that the NK cell line KHYG-1 predominantly released EVs containing CD81 and not CD63, and that these vesicles contained low amounts of cytolytic proteins and lacked in killing activity towards tumor targets." (PMID 36189227, 2022). "Therefore, GW4869 decreases release in EVs of syntenin-1 and LAMP1, but not the other proteins, including CD63, and it conversely tends to increase release of larger/heavier EVs, as previously observed in other tumor cells." (PMID 34282141, 2021). "Other studies have shown that CD63+/CD9+/Flotillin-1+ EVs from NPC (CNE2, CNE1, 5-8F, 6-18B) cells were enriched with a key glycolysis-regulatory enzyme, 6-Phosphofructo 2-kinase/fructose 2, 6-bisphosphatase 3, which promotes angiogenesis amongst other tumor permissive activities." (PMID 33158181, 2020). "There were some vesicles which were not labeled with CD63 and this could be a result of heterogeneity found in EV signatures in tumor cells." (PMID 30918474, 2019). "Tumor blood vessels also expressed CD63, although not always adjacent to CD63+ tumor cells." (PMID 29523123, 2018). "Unlike their expression in other tumor types, the constitutive expression of CD63 may indicate that this factor does play a direct role in human gastric carcinogenesis." (PMID 21521534, 2011). "Interestingly, EV marker CD63 was absent, suggesting this may be a tumor-specific feature, while CD81 was in enriched in RR-derived sEVs." (PMID 40568172, 2025). "The exosomal surface CD63 in the CD63+ CAF-derived exosomes induces STAT3 activation in the recipient cells, which may be responsible for the different role of exosomal miR-22 in the induction of drug resistance in tumor cells compared to its intracellular source." (PMID 37048103, 2023). "In addition, to be potential candidates for cancer biomarkers, a recent study using immunohistochemistry (IHC) showed that tumor exosomal CD9 and CD63 might also act as potential prognostic monitors due to the increased expression in rectal tumor tissue after chemoradiation treatment." (PMID 35757760, 2022). "However, CD63 expression pattern did not correlate with any tumor staging." (PMID 21521534, 2011). "THBS2 showed a significant correlation (P < 0.05) with tumor size in CD81 capture for all three groups but not for the CD9 and CD63 capture or the average capture (except the average capture in the all subject group, which has a P value of 0.02)." (PMID 40897818, 2025). "Currently, methods for early detection of BrCa are lacking, but there are several leads for new tumor markers, including CA125, CA15‐3, and CD63 glycovariants." (PMID 34423573, 2022). "Consistent with some previous reports, our findings revealed that CD63 inhibits HCC cell proliferation and migration in vitro, and results of animal experiments confirmed its negative role in tumour growth in vivo." (PMID 33277798, 2021). "Based on the results that MAC did not change the protein levels of PD-L1 and CD63 in the same protein amount of EVs, we confirmed that MAC inhibited EV PD-L1 by inhibiting EV secretion without impediment of PD-L1 sorting from tumor cells to EV." (PMID 35265193, 2022). "Moreover, SP-IRIS demonstrated the presence of EVs that were double-positive for CD9, CD63, and CD81 and negative for the platelet marker CD41, which indicated low contamination of blood-derived EVs in the tumor EV isolates." (PMID 36531960, 2022). "To test whether EVs are secreted by the grafted tumour human PC9 cells, we exploited anti-CD63 antibody that are highly specific to CD63 originating from human (PC9) but not murine cells." (PMID 34725463, 2021). "The recognized exosomal markers CD63, CD9, and CD81, are not tumor-specific." (PMID 34707986, 2021).
tumor (continued). "The present study investigates the structure-function relationship of TIMP-1 for its interaction with CD63, which may eventually help design a novel approach for targeting TIMP-1’s pro-oncogenic activity without interfering its tumor suppressive MMP-inhibitory function." (PMID 32034211, 2020).
cancer (254 papers, 2009 to 2026). A tumor composed of atypical neoplastic, often pleomorphic cells that invade other tissues. "This aligns with the association of CD63 with less aggressive cancer phenotypes and its inverse correlation with metastasis." (PMID 40411659, 2025). "It is known that in several human tumors, TIMP-1, once released from cancer or stromal cells, associates with CD63 at the cell surface, exerting its oncogenic role." (PMID 37443843, 2023). "TIMP-1 has been reported to act in a growth-stimulatory manner on many cancer cells, including BC cells, and CD63 and ITGB1 were linked to drug resistance of BC cells." (PMID 36291767, 2022). "We also observed a ~32-fold upregulated expression of CD63, a diagnostic marker of PC and key component of cancer stem cell-derived extracellular vesicles involved in the maintenance of stemness phenotype." (PMID 36428807, 2022). "This in-depth analysis of the CD63 interactome provide insights regarding possible therapeutic targets or biomarkers for EBV-associated cancers." (PMID 33920772, 2021). "CD63 has previously been associated with cancer; however, the expression pattern differs dependent on the specific cancer type." (PMID 29523123, 2018). "We further identified the association between COX7B and CD63 and observed that 59% of the 32 cancer types in TCGA show a positive correlation with COX7B." (PMID 30367559, 2018). "The involvement of CD63 in cancer metastasis and its loss in tumors described in this study, is in concordance with a poorer overall survival of patients in the yellow cluster." (PMID 26979459, 2016). "In this study, we demonstrate that cancer malignancy associated with the glycosylation of CD63 is regulated by RPN2." (PMID 24884960, 2014). "There have been several papers on the association between CD63 and cancer." (PMID 36362598, 2022). "In addition to mediating early and final events of platelet activation such as platelet recruitment and fibrinolysis, CD63 is associated with signalling in cancer." (PMID 33923802, 2021). "Moreover EVs are becoming increasingly important in monitoring cancer progression and therapy, since they are able to carry specific disease biomarkers such as Glypican-1, colon cancer-associated transcript 2, CD63, CD24, and many others." (PMID 31281356, 2019). "CD63-positive exosomes might be associated with the interaction between stromal cells and cancer cells." (PMID 30222750, 2018). "There have been several articles regarding the association between CD63 and cancer." (PMID 30222750, 2018). "CD63-positive exosomes might be associated with the malignant potential of cancer cells through the interaction between stromal cells and cancer cells." (PMID 30222750, 2018). "Therefore, to evaluate whether CD63 was associated with cancer malignancy, it was essential to evaluate both the glycosylation and expression level of CD63." (PMID 24884960, 2014). "Proteins carried by naturally occurring exosomes, including Tsg101, Alix, Rab, CD63/81, and Hsp90, can transmit information and regulate immune responses, indicating that exosomes can help develop new cancer vaccines 265,266." (PMID 39744442, 2025). "Cancer cells expressing CD63-Antares2, which emits luminescence, were implanted into mice to provide a xenograft animal model in which cancer-targeting medications can be investigated as an exosome imaging tool." (PMID 40095345, 2025). "We successfully profiled EVs derived from human cancer cell lines and a plasma cancer patient using aptamers against the most typical exosomal CD63 and cancer EpCAM proteins." (PMID 41373484, 2025). "The novel sEVs sensing MJP system was characterized through both theoretical and experimental methods, showing reliable performance in identifying the cancer cell OECM-1-derived sEVs using the CD63 surface marker." (PMID 40352358, 2025). "The elevation of Ca2+ levels in cancer cells stimulated a 5-fold increase in release of CD63+CD9+ALIX+ exosomes." (PMID 40121518, 2025).